CDK4 (cyclin dependent kinase 4)
Diseases named in the same sentence as CDK4 in open-access papers (continued):
Sharing a sentence is not in itself a finding about the gene and the disease.
cancer (continued). "Clinical inhibitors of CDK4/6 kinases have been approved as a therapeutic for estrogen receptor-positive breast cancers, and more than 100 clinical trials are currently evaluating CDK4/6 inhibitors in cancer treatment." (PMID 34099663, 2021). "Due to the critical roles of the CDK4/6/Rb pathway in cell cycle arrest and apoptosis, CDK4/6 inhibitors have emerged as promising candidates for cancer treatment." (PMID 33925607, 2021). "Herein, we used NGS to interrogate the complex genomic landscape of 2457 patients with diverse cancers, of whom 507 patients harbored specific, potentially sensitizing G1/S phase cell-cycle (CDK4/6, CCND1/2/3, or CDKN2A/B) gene alterations." (PMID 33427211, 2021). "These are specific for CDK4 and CDK6 and can bind in presence or absence of cyclin D. Changes in the expression level or mutations in cyclin D1, CDK4, CDKI and pRB are strongly implicated in cancer." (PMID 34198779, 2021). "In summary, these results established that CK1ε inhibitor D 4476 potentiates the therapeutic efficacy of CDK4/6i ribociclib in retarding tumorigenesis, providing a novel and effective cancer treatment strategy." (PMID 34508104, 2021). "The cyclin D-CDK4/6 complex is hyperactivated in many types of human cancers in which the CDK4/6–RB pathway is dysregulated." (PMID 34070562, 2021). "CDK4 inhibition is featured as a potential strategy for targeted treatment of several cancers leading to cell cycle arrest within the G1 phase 1." (PMID 33919867, 2021). "While the RB1 gene is rarely altered in these cancers, the RB1 protein is disabled by cyclin E, CDK2 and/or CDK4/6 upregulation as well as by loss of the CDK inhibitors, p27 and p16INK4a, in essentially all MPNSTs." (PMID 34065204, 2021). "Treatment of cells with 5-FU leads to the accumulation of cells in the S-phase, and treatment of cells with CDK2 or CDK4/6 inhibitors prevents the phosphorylation of tumor suppressor RB, thereby invoking cancer cell cycle arrest in the G1 phase." (PMID 33767584, 2021). "This study aimed to characterize the value of combining a PARP inhibitor with a CDK4/6 inhibitor for cancer therapy." (PMID 33923231, 2021). "The upregulated of cyclin B1, cyclin B2, and CDK4 indicated the radiation treatment stimulates the subpopulation of cancer-stem-like cells cell cycle progression and proliferation." (PMID 33931075, 2021). "In NSCLC, E2F3 improves the malignancy of cancer cells by increasing the expressions of cyclinD1, cyclinD2, and CDK4 while inhibiting p21 and p57 expressions." (PMID 34346845, 2021). "To develop a treatment strategy for cancers resistant to CDK4/6 inhibitors, here, we established palbociclib-resistant sublines and analyzed their resistance mechanisms." (PMID 34244855, 2021). "Small molecule inhibitors of CDK4/6 are used and tested in clinical trials to treat multiple cancer types." (PMID 34099663, 2021). "We found that CDK4 was highly expressed in most cancers and that CDK4 performance levels significantly correlated with the prognosis of cancer patients." (PMID 34422248, 2021). "In particular, CDK4 is anticipated to become a crucial hub gene to snipe the metastasis of cancer cells in HCC." (PMID 34784846, 2021). "Recently, multiple inhibitors for CDK4/6 such as palbociclib, abemaciclib, or ribociclib have been developed to suppress cyclin D-CDK4/6 driven proliferation of cancer cells." (PMID 34413284, 2021). "We expressed and purified novel anti-CDK4 scFv antibody AK2 to target CDK4 as an important anti-cancer therapeutic strategy." (PMID 34930213, 2021). "The CDK4 positively regulates cancer stemness in triple-negative BC, where it behaved as negative prognostic marker and therapeutic target." (PMID 34778245, 2021). "Our findings suggest new applications of previously approved CDK4/6 inhibitory drugs and novel HSP90 inhibitory agents in combination therapies in multiple cancer types including Rb-deficient tumors." (PMID 34686682, 2021).
cancer (continued). "The results of this study demonstrate that use of an anti-CDK4 scFv antibody is an exciting and promising strategy for achieving CDK4-targeted cancer diagnosis, prognosis and treatment." (PMID 34930213, 2021). "It has been reported that CDK4/6 inhibitors can inhibit cancer cell cycle progression because of P16 gene deletion." (PMID 34123801, 2021). "Since the frequent deregulation of CDK-4 in cancer often leads to addiction to its activity, it is emerging as a bright therapeutic target." (PMID 33732631, 2021). "The clinical synergism between PARPi and CDK4/6i is now under clinical investigation in different cancer settings." (PMID 34204543, 2021). "Through analytical chemical analysis, the results of CDK4 in the clinical prognosis or pathogenesis of different cancers were verified." (PMID 34422248, 2021). "De novo or acquired resistance to CDK4/6 inhibitors is a common occurrence in anti-cancer treatment." (PMID 33628597, 2021). "One of the main alterations observed in cancer concerns cyclin D and CDK4/6 overexpression, and in particular, cyclin D alteration is one of the key hallmarks of MM." (PMID 34830893, 2021). "Dysregulation of the CDK4/6-Rb pathway, as with the activation of CCND1/CDK4 or CDKN2A loss, contributes to cancer development and confers resistance of cancer cells to treatment with the MAPK/ERK inhibitors." (PMID 33807122, 2021). "Metabolic rewiring is consistently observed in cancer cells and is an emergent mechanism of resistance to CDK4/6 inhibition." (PMID 33599863, 2021). "Cyclin-dependent kinase 4/6 (CDK4/6) inhibitors have garnered interest as cancer treatments due to their efficiency in inhibiting cell proliferation." (PMID 34784791, 2021). "We discovered a novel mechanism of regulation of HIF-1α, involving Smurf2 E3 ubiquitin ligase, in CDK4/6 inhibitor treated cancer cells where HIF-1α is destabilized." (PMID 34611473, 2021). "Although topoisomerases 2 and CDK4/6 inhibitors have emerged as a potent strategy for cancer treatment, few studies have tested these compounds in clinical trials for ReCa treatment." (PMID 34771654, 2021). "As their primary goal is to halt the cell cycle, CDK4/6i can induce a transient senescence of cancer cells, and therefore, their ability to produce a damaging SASP must be considered." (PMID 34137158, 2021). "Likewise, blocking p130 degradation could phenocopy CDK4/6 inactivation and could potentially be therapeutically advantageous, and would be consistent with our analysis showing that loss-of-function in cyclin D, CDK4, and cyclin F are highly correlated across nearly 800 cancer cell lines." (PMID 34851822, 2021). "CDK4 is the basic driving factor of the cell cycle and is essential in the initiation and development of various malignant tumors." (PMID 34120619, 2021). "In this review, we discuss the recent advancements in the development of circulating biomarkers of CDK4/6i response in patients with HR+/HER2−breast cancer." (PMID 34072070, 2021). "As the use of CDK4/6 inhibitors in cancer therapies becomes more prominent, an understanding of their effect on the cell cycle becomes more urgent." (PMID 34784791, 2021). "The link between metabolism and cell-cycle regulators has garnered significant interest, and the role of CDK4/6 in metabolic reprogramming is an area of active investigation in multiple types of cancer." (PMID 33572972, 2021). "Consistently, CDK4/6 inhibitors and PARP inhibitors have been tested in a number of clinical trials for the treatment of cancer cells with compromised DNA repair, e.g., BRCA1/2 mutations." (PMID 33809714, 2021).
cancer (continued). "As previously quoted, palpociclib induces autophagy in cancer, targeting CDK4 and CDK6, via the LKB1 and Ser325 phosphorylation resulting in a CCND1-mediated, reduced activation of AMPK." (PMID 34445095, 2021). "Out of these proteins, the CDK4 is a regulatory component of the DC complex which is a major integrator of various mitogenic and antimitogenic signals, plays a vital role in cancer." (PMID 33438725, 2021). "Our study highlights a wide-spread reduction in sensitivity to anti-cancer drugs accompanied with an acquired vulnerability to EGFR inhibitors following CDK4/6 inhibitor treatment." (PMID 34944934, 2021). "Several CDK4/6 inhibitors are in use to treat a variety of cancers with hyperactive CDK4/6-cyclin D1." (PMID 34065983, 2021). "Mechanistically, TFAP2A-AS1 exhibits its cancer-promoting role in NSCLC through adjusting the miR-584-3p/CDK4 axis." (PMID 37305398, 2021). "Selective CDK4/6 inhibitors palbociclib, ribociclib and abemaciclib have been developed and are undergoing clinical trials in a variety of cancers." (PMID 34136392, 2021). "We found that mesenchymal cancer cells had lower levels of p21 in the CDK4-p21 complex, which explains their increased CDK4 activity." (PMID 34309585, 2021). "The CDK4/6-Cyclin D-Rb pathway is one of the most frequently dysregulated in cancer and more than 40% of human cancers show alterations in CDKs or cyclins." (PMID 33374971, 2020). "On the other hand, when applied sequentially CDK4/6 inhibitors have recently been shown to enhance cytotoxicity by preventing recovery of cancer cells as shown in pancreas cancer." (PMID 33255177, 2020). "The inhibition of cyclin D1 and CDK4/6 has been considered a promising strategy for the treatment of cancers including TNBC." (PMID 32508655, 2020). "Only an exact analysis and understanding of the overlapping and unique consequences of treatments with different inhibitors will enable the optimization of treatment schedules and expansion of administration of CDK4/6 inhibitors to various types of cancers." (PMID 33255177, 2020). "More recently a quinazolinone-based dual inhibitor of CDK4 and tubulin polymerization has been reported for anti-cancer therapy." (PMID 32974274, 2020). "Previous studies revealed the positive correlation between elevated CDK4 expression and increased therapeutic activity of CDK4/6 inhibitors undergoing clinical trials or currently used in anti-cancer therapy." (PMID 33114713, 2020). "It therefore appeared that the combined inhibition of CDK4/6 and PARP showed synergy to increase DNA damage in RB-deficient cancer cells through ROS." (PMID 32249776, 2020). "In conclusion, we show that VHL- and IAP-based PROTACs are an attractive approach for targeted degradation of CDK4/6 in cancer." (PMID 33133483, 2020). "The dataset-based cancer genome study from 482 invasive BC patients showed that 27.4% of CDK4/6–RB axis genetic deregulation involves either the expression of single gene alteration or multiple gene alterations in combination." (PMID 32183020, 2020). "Although CDK4/6i has been approved by the FDA, the molecular mechanism of CDK4/6i in cancer treatment has remained elusive." (PMID 32249776, 2020). "CDK4/6 is the main driving factor in cell cycle regulation and plays a key role in the occurrence and progression of various malignant tumors." (PMID 32357912, 2020). "Cancer cells overcome the Rb-dependent restriction point through alterations that lead to constitutive activation of cyclin D-cyclin-dependent kinase 4/6 (CDK4/6)." (PMID 32626773, 2020). "CDK4/6 inhibitors inhibit the progression of cancer cells from G1 to S phase and trigger G1 cell cycle arrest by selectively inhibiting the function of CDK4/6." (PMID 32708403, 2020).
cancer (continued). "Given the recent use of palbociclib in clinical trials for NSCLC patients, understanding the functional consequences of CDK4/6 inhibition on cancer cell metabolism are important for identifying potential combination therapies to improve patient outcome." (PMID 32624705, 2020). "The course of the disease in patients with CDK4/6 inhibitor-associated MRONJ and cancer from the cohort was registered." (PMID 33353034, 2020). "In conclusion, in this study we report the first triple action single-molecule inhibitor SRX3177, which disrupts cancer cell signaling through simultaneously inhibiting CDK4/6, PI3K, and BRD4." (PMID 32793389, 2020). "Over-activation of the CDK4/6-cyclin D-Rb-E2F pathway has been observed in many cancers, including that of breast." (PMID 32650578, 2020). "CDK4 is known to accelerate the G1 and G2 mitotic phases, providing a cell division advantage to cancer cells." (PMID 33180876, 2020). "Beyond the inhibition of cell proliferation, all the FDA approved CDK4/6 inhibitors exert other effects on cancer cells and tumor microenvironment, as recently reviewed by our group." (PMID 33374971, 2020). "CDK4 inhibitors are a new class of anti-cancer drugs that commonly used in the treatment of metastatic BC." (PMID 32670874, 2020). "The cdk4, cdk6, rb1, and e2f1 genes are expressed in a wide range of cancers according to analysis of the TCGA PANCAN database, which is composed of 12,839 samples." (PMID 32357912, 2020). "Cyclin-dependent kinase 4/6 controls the downstream transcriptional signals that regulate cancer cell proliferation through the phosphorylation of their canonical substrate RB1." (PMID 33282875, 2020). "The cdk4/6 genes are generally expressed among various cancers, and their expression is higher or lower than that of normal tissues in most cancer types." (PMID 32357912, 2020). "Inhibition of CDK4/6 in combination with anti-EGFR therapy has been a recent approach used in cancer therapeutics, including the treatment of HNSCC." (PMID 33302499, 2020). "Numerous pre-clinical studies have demonstrated the beneficial effects of CDK4/6 inhibition for RB1-positive human cancers; however, drawbacks of this targeted therapy are coming to light." (PMID 32344731, 2020). "Fascaplysin was reported to be a potent inducer of cancer cell apoptosis mainly exerted via cyclin-dependent kinase 4 (CDK4) inhibition and suppression of angiogenesis." (PMID 32967369, 2020). "Multiple preclinical studies have demonstrated the radiosensitization effects of CDK4/6 inhibitors in various cancer types." (PMID 32933570, 2020). "The core regulatory effect of CDK4/6 in the cell cycle illustrates its vital role as a target in the treatment of malignant tumors." (PMID 32357912, 2020). "Pharmacologic inhibitors of CDK4/6 have recently shown the promising activity in patients with cancers." (PMID 32984335, 2020). "It has been previously reported that the expression of CyclinD1 and CDK4 results in multiple cancer hallmarks by promoting the proliferation of cancer cells." (PMID 32015423, 2020). "The selective anti-RCC activity of ribociclib as a single agent is consistent with the fact that the CDK4/6 pathway plays a crucial role in the proliferation and progression of cancer and serves as a promising therapeutic target in various human malignances." (PMID 32626773, 2020). "More large-scale prospective clinical trials are needed to validate the curative effect of CDK4/6 inhibitors in more cancer types and more combination models." (PMID 32357912, 2020). "CDK4/6 inhibitors, which have broad potential for the treatment of cancers, including MM28, should counteract the Warburg effect, and HIF1α appears to be a potent target for antimyeloma therapy." (PMID 32709889, 2020). "As a result of CDK4/6 activation, cancer cells are driven toward progression into the DNA synthetic (S) phase of the cell cycle." (PMID 32249776, 2020).
cancer (continued). "We further demonstrate that concurrent disruption of the acetyllysine binding function of BRD4 and the kinase activities of PI3K and CDK4/6 by the TP inhibitor improves efficacy in several cancer models." (PMID 32694708, 2020). "In this scenario, the development of CDK4/6 inhibitors has been the most interesting finding, since the vulnerability of cancer cells has been fought maintaining a tolerable toxicity profile." (PMID 32899866, 2020). "The adopted therapeutic strategies have been reported for patients taking CDK4/6 inhibitors and for other cancer patients of the cohort as well." (PMID 33353034, 2020). "Cyclin D1 protein, one of the most important oncoproteins in human cancer, accelerates cell proliferation by engaging CDK4/6 to phosphorylate Rb and drive G1–S transition." (PMID 33139730, 2020). "These include well-known cancer-associated genes, such as CCND1 (25 tumors), CDK4 (25 tumors), MDM2 (23 tumors), SETDB1 (23 tumors), ERBB3 (11 tumors), ERBB2 (11 tumors), MYC (10 tumors) and MYCN (five tumors)." (PMID 32025003, 2020). "The potential application of CDK4/6 inhibitors has been widely recognized, and CDK4/6 inhibitors are considered a major breakthrough in cancer treatment." (PMID 32651427, 2020). "For example, p16INK4a is a known tumor repressor in several cancers by binding to and inhibiting cyclin-dependent kinases 4/6(CDK4/6)." (PMID 32210733, 2020). "We further investigated the effects of CDK4/6 inhibition on cancer cell metastasis in a xenograft metastasis model." (PMID 32296027, 2020). "In this study, we describe the first in class rationally-designed triple activity inhibitor that concomitantly disrupts functions of three critical targets based upon known synthetic lethality relationships in cancer cells—CDK4/6, PI3K, and BRD4." (PMID 32793389, 2020). "The impact of CDK4/6 inhibitors on cell metabolism has been more extensively studied in estrogen receptor (ER)-positive breast cancer, the only type of cancer in which these drugs have received FDA-approval so far." (PMID 32708306, 2020). "The insulin-, the IGF-1-, and the leptin-induced signaling cascades converge on activation of PI3K/AKT-mTOR pathway, which stimulates cancer cell proliferation and survival, the latter being also stimulated by the estrogen-induced CDK4/6." (PMID 33271979, 2020). "The recurrence of these changes suggests that annulment of the G1 checkpoint and speeding up of the CDK-4/cyclin D pathway creates favorable circumstances for the multiplication and survival of cancer cells." (PMID 33841550, 2020). "A molecular analysis of cell cycle markers such as p21, p27, cyclin D1, and CDK4 also provided strong proof of cell cycle arrest, which leads to apoptosis induction in cancer cells." (PMID 31979292, 2020). "These factors, produced by amniotic stem cells, can regulate the expression of cancer cell proteins associated with the cell cycle, such as cyclin-dependent kinases (CDK2, CDK4, CDK6) and cyclins (cyclin D2, cyclin E1, cyclin H)." (PMID 32972410, 2020). "Conversely, it was highly likely that cancer cells depended on the CDK4/6 complex to survive DNA damage." (PMID 32249776, 2020). "CDK4/CDK6 inhibitors are among the most exciting new anti-cancer drugs of the past 10 years, and are approved by the FDA for patients with ER+HR− breast cancer." (PMID 32198354, 2020). "As a result, nc886− cells are hyperactive in the progression of the G1 to S cell cycle phase, proliferate faster, and are more sensitive to palbociclib, which is a cancer therapeutic drug that targets CDK4/6." (PMID 32225025, 2020). "Since uncontrolled cell proliferation is a hallmark of cancer cells, it has been postulated that genes inhibiting RB function, including CCND1 and CDK4, act as oncogenes." (PMID 32244804, 2020). "Ribociclib was the second selective CDK4/CDK6 inhibitor to gain the market approval as a cancer therapy in combination with an aromatase inhibitor." (PMID 32373584, 2020).